INS (insulin)
Diseases named in the same sentence as INS in open-access papers (continued):
Sharing a sentence is not in itself a finding about the gene and the disease.
Insulin resistance (continued). "REPS1 phosphorylation correlates with insulin sensitivity and is impaired in insulin resistance, highlighting its role in metabolic regulation." (PMID 40482643, 2025). "Vitamin D receptors are present in pancreatic β-cells, where vitamin D regulates insulin secretion by modulating β-cell function and suppressing adipogenesis, thereby reducing insulin resistance." (PMID 41305618, 2025). "Pathologically, excessive hepatic fat accumulation disrupts insulin signaling, contributing to insulin resistance and increased glucose production." (PMID 40551893, 2025). "In particular, although the participants have no medical history of T2D, the patients with higher %WR have higher fasting levels of glucose, insulin, C-peptide and insulin resistance, as well as lower insulin sensitivity." (PMID 40687579, 2025). "The upregulation of genes related to glucose uptake and insulin signaling pathways following green tea treatment highlights its potential as a supplementary approach for managing insulin resistance and type 2 diabetes." (PMID 40522107, 2025). "Insulin resistance primarily occurs in insulin target organs such as skeletal muscle, adipose tissue, and the liver, leading to reduced glucose uptake, increased gluconeogenesis, and elevated blood glucose levels." (PMID 40458823, 2025). "In patients with PCOS, adverse associations were observed between carbohydrate metabolism parameters and insulin resistance indices, while insulin sensitivity indices correlated positively with adiponectin and omentin concentrations." (PMID 41303021, 2025). "Aside from lifestyle modifications, continuous subcutaneous insulin infusion can ameliorate insulin resistance and hyperinsulinemia, thereby improving glucose toxicity compared with multiple injection insulin treatment." (PMID 39998445, 2025). "Several evidence show that TRE do not influence fasting and postprandial insulin levels, while other studies suggest TRE effectiveness in reducing insulin levels and ameliorating insulin-resistance." (PMID 39899119, 2025). "Type 2 diabetes mellitus (T2DM) is a disease caused by a complex interplay of genetic, epigenetic, and environmental factors and is characterized by insulin resistance and insufficient insulin secretion." (PMID 40831950, 2025). "A human intervention study further showed that pasteurized A. muciniphila improved insulin sensitivity, reduced insulin and cholesterol levels, and altered body fat distribution in overweight/obese individuals with insulin resistance." (PMID 41568048, 2025). "A study on women with gestational diabetes revealed significant increases in fasting insulin and related factors, highlighting the relationship between elevated insulin levels and insulin resistance." (PMID 40002771, 2025). "Regarding MASLD patients, treatment with phlebotomy has been reported to improve insulin resistance, evaluated by fasting serum glucose, insulin levels, and the homeostatic model assessment-insulin resistance (HOMA-IR) score." (PMID 39941760, 2025). "These values show that the cafeteria-style diet promotes the development of insulin resistance and pancreatic hyperfunction by increasing insulin secretion, and trkB receptor antagonism with ANA-12 exacerbated the effects of the cafeteria-style diet." (PMID 39857710, 2025). "At the end of the experiment (17th week), the DKD group displayed significantly elevated FBG levels, fasting plasma insulin levels, and the homeostatic model assessment of insulin resistance (HOMA-IR) index compared to the NC group (P < 0.001)." (PMID 41585896, 2025). "In the state of insulin resistance, the effect of insulin in promoting muscle protein synthesis is weakened, and it also interferes with the transport and utilization of amino acids, resulting in a decrease in muscle mass." (PMID 40873790, 2025). "Insulin resistance (IR), i.e. insufficient glucose uptake by cells after insulin stimulation, primarily affects adipose tissue, muscles and liver." (PMID 40425812, 2025).
Insulin resistance (continued). "Leptin is also essential for central insulin signaling, meaning that individuals with excess adipose tissue commonly exhibit acquired insulin resistance." (PMID 40724604, 2025). "In its original description, it was found to have a good correlation with the euglycemic–hyperinsulinemic clamp, ectopic fat accumulation, and fasting insulin levels, which makes it a reliable indicator of overall insulin resistance." (PMID 40218212, 2025). "Plasma bilirubin levels have been directly linked to insulin sensitivity, and reduced levels in humans are associated with higher HOMA‐IR and insulin resistance." (PMID 40022609, 2025). "The HOMA2 calculator determined β-cell function (HOMA%B), insulin sensitivity (HOMA%S), and insulin resistance (HOMA2IR) by analyzing fasting serum insulin and glucose levels." (PMID 40519702, 2025). "Insulin resistance contributes to the downregulation of muscle contractile protein synthesis by inhibiting insulin’s anabolic signaling pathway and simultaneously upregulating protein degradation via the ubiquitin–proteosome pathway." (PMID 40722684, 2025). "Insulin resistance (IR) is the cornerstone of type 2 diabetes, characterized by reduced insulin secretion or inadequate sensitivity to insulin." (PMID 40313594, 2025). "A plethora of studies have demonstrated that the diversity of the gut microbiome plays a crucial role in maintaining optimal insulin sensitivity and mitigating insulin resistance." (PMID 40896191, 2025). "This adipocytokine possesses anti-inflammatory and insulin-sensitizing properties, and it is downregulated in obesity, leading to insulin resistance and metabolic dysfunctions." (PMID 41155431, 2025). "Impaired glucose tolerance (IGT), along with impaired fasting glucose (IFG) and elevated glycated haemoglobin (HbA1c), are recognized as contributing factors to moderate insulin resistance in insulin-dependent tissues." (PMID 39861423, 2025). "Genetic polymorphism studies have identified that the intron 7 Clu variant at rs2279590 is associated with insulin resistance (HOMA-IR) and disorders of insulin secretion (HOMA-β) among diabetes patients." (PMID 40438587, 2025). "Hypernatremia can exacerbate insulin resistance, as high sodium levels have been shown to impair insulin signaling pathways." (PMID 40136609, 2025). "Serum cortisol levels are associated with insulin secretion, and the PAC is associated with insulin resistance in patients with untreated type 2 diabetes." (PMID 40296149, 2025). "Type 2 diabetes mellitus (T2DM) is a chronic, serious disease characterized by an unbalance of carbohydrate, lipid, and protein metabolism in the blood, along with insulin resistance, and inadequate insulin production." (PMID 40190404, 2025). "Further analyses, such as serum insulin measurements or insulin tolerance tests, would help to distinguish between insulin resistance and β-cell dysfunction." (PMID 41057543, 2025). "A study conducted on knockout VDR mice showed impairment in insulin resistance, and supplementation with vitamin D did improve insulin secretion by stimulating the pancreatic beta cells." (PMID 40004770, 2025). "Insulin resistance (IR) is the state of decreased sensitivity and reactivity to the effects of insulin." (PMID 41040505, 2025). "In rodent models exhibiting insulin resistance, intravenous delivery of recombinant adiponectin has been shown to restore normal insulin sensitivity." (PMID 41373994, 2025). "A proinflammatory cytokine cascade, including interleukin-6, tumor necrosis factor-alpha, and Interleukin-1 beta, disrupts insulin signaling pathways and leads to insulin resistance." (PMID 40725663, 2025). "On a cellular level, insulin resistance is defined as the insufficient strength of insulin signaling from the insulin receptor (InsR) downstream to the final substrates, compromising numerous metabolic aspects of cellular function." (PMID 40277891, 2025).
Insulin resistance (continued). "A decreased insulin metabolism leads to chronically elevated levels of circulating insulin that can further promote the development of insulin resistance." (PMID 39384641, 2025). "These pathways are activated in inflammatory cells in liver, muscle, and adipose tissue, leading to a vicious cycle of diminished response to insulin in these tissues, exacerbating insulin resistance." (PMID 40235664, 2025). "ESR1-specific signaling in adipocytes has been shown to promote insulin sensitivity, and reductions in ESR1 have been linked to obesity and insulin resistance." (PMID 39833659, 2025). "The presence of α-MSH in CNS enhances insulin sensitivity, whereas α-MSH causes insulin resistance in peripheral tissue." (PMID 41002740, 2025). "The more common type, type II diabetes mellitus (T2DM), results from insulin resistance due to functional defects of β-cells and impaired insulin sensitivity and cell uptake and is highly connected to a diet rich in sugars and fat and a sedentary lifestyle." (PMID 40243689, 2025). "During pregnancy, insulin resistance occurs because of the secretion of placental hormones that antagonize insulin." (PMID 41488874, 2025). "It is known that MASLD via mechanisms of increased oxidative stress, inflammation and lipotoxicity worsens insulin resistance, and cirrhosis, by decreasing hepatic insulin clearance, also contributes to insulin resistance." (PMID 40444235, 2025). "In conditions of insulin resistance, the ability of skeletal muscle to uptake glucose in response to insulin is markedly impaired." (PMID 40004800, 2025). "M1 MΦs secrete pro-inflammatory cytokines, such as tumor necrosis factor-alpha (TNF-α), interleukin-6 (IL-6), and interleukin-1 beta (IL-1β), which impair insulin signaling in adipocytes and contribute to insulin resistance." (PMID 41602577, 2025). "It has been known that HFD induces insulin resistance by modulating several insulin signaling pathway proteins." (PMID 39747658, 2025). "EMO can reduce hepatic lipogenesis and increase insulin sensitivity to combat insulin resistance (IR) by upregulating phosphatidylinositol 3-kinase (PI3K), AKT2, and AMPKα." (PMID 40727101, 2025). "Protocatechuic acid enhances the release of insulin, while catechin improves insulin resistance and lowers blood glucose sources." (PMID 41031259, 2025). "As STZ is particularly toxic to insulin-producing cells, it has been extensively used as an experimental model for peripheral toxicity as well as neurotoxicity by inducing insulin resistance." (PMID 40108007, 2025). "Insulin resistance refers to the decreased sensitivity of the body to insulin, leading to a reduced efficiency in insulin’s promotion of glucose uptake and utilization." (PMID 41358005, 2025). "Lastly, it was found that Rock-1 expression levels are inhibited by the overexpression of miR-135, miR-214, and miR-202, which leads to insulin signaling and insulin resistance." (PMID 40565979, 2025). "Physiological changes such as the completion of puberty, increased insulin resistance, and early adulthood weight gain likely contributed to the increased insulin requirements observed in this period." (PMID 41143600, 2025). "The homeostasis-model-assessment-estimated insulin resistance (HOMA-IR) was calculated to estimate insulin sensitivity by using the fasting plasma glucose and insulin concentrations." (PMID 40332596, 2025). "Since glucose can regulate its uptake and metabolism in muscle independently of insulin, the presence of hyperglycemia in T1D may provide a compensatory mechanism to maintain a relatively “normal” glucose disposal in the presence of insulin deficiency or insulin resistance." (PMID 39998445, 2025). "The main limitations of the study include the use of sub‐populations for serum insulin, insulin resistance markers, and neuroimaging measures." (PMID 40478656, 2025).
Insulin resistance (continued). "IFN-γ-induced inflammation contributes to insulin resistance by interfering with insulin signaling in adipocytes, hepatocytes, and skeletal muscle." (PMID 40573106, 2025). "Insulin resistance (IR) is a physiological state in which cells are unable to respond to the standard activities of the hormone insulin." (PMID 40406487, 2025). "In horses, another perissodactyl, a positive correlation was found between ferritin and the insulin response, indicating a possible link between iron overload disorder and insulin resistance." (PMID 40510676, 2025). "Hyperglycemia can result from either reduced insulin secretion due to β-cell dysfunction or insulin resistance (IR), which impairs glucose uptake." (PMID 40509433, 2025). "Preserving insulin homeostasis and reducing peripheral insulin resistance remain the ideal goals for managing T2DM." (PMID 39996055, 2025). "The development of insulin resistance has been proposed to be a defense mechanism of the body protecting insulin-sensitive tissues against fuel overload and fuel toxicity (see also below)." (PMID 41009753, 2025). "Chronic inflammation often intensifies insulin resistance, while pancreatic islet cell damage impairs insulin secretion, together characterizing CFRD." (PMID 41300682, 2025). "Studies have demonstrated that berberine enhances cellular insulin sensitivity and ameliorates insulin resistance by modulating key components of the insulin signaling pathway—including InsR, IRS-1, AKT, and AMPK." (PMID 41471379, 2025). "Adiponectin serves as a reliable marker for insulin sensitivity, with its levels inversely correlating with the degree of insulin resistance and metabolic dysfunction." (PMID 40722684, 2025). "The elevated level of energy substrates and the inflammatory environment with excess calorie uptake result in the overproduction of mitochondrial ROS that suppresses insulin signaling and leads to the development of insulin resistance." (PMID 40290438, 2025). "Individuals with obesity exhibited significantly impaired glucose metabolism, characterized by elevated fasting glucose, insulin, and insulin resistance, as assessed by HOMA-IR." (PMID 39861442, 2025). "As mentioned, ectopic fat accumulation in both skeletal muscle and the liver increases insulin resistance (IR) and impairs insulin action." (PMID 41255523, 2025). "Hippurate treatment inhibits lipid accumulation and rescues insulin resistance induced by 24-hour chronic insulin in IHH." (PMID 39746606, 2025). "Low–glycemic‐index (LGI) diets, which emphasize slowly digestible carbohydrates, attenuate postprandial glucose excursions and enhance insulin sensitivity, as evidenced by reductions in the Homeostasis Model Assessment of Insulin Resistance (HOMA-IR)." (PMID 40775771, 2025). "This further indicates that the insulin responsiveness of cells grown in LG + Insulin condition is reduced and the cells have developed insulin resistance." (PMID 39471069, 2025). "LASSBio-2129 was selected to evaluate the hepatic and skeletal muscle glycogen content and insulin sensitization in a dexamethasone-induced insulin resistance model." (PMID 41155701, 2025). "IL-1β, for instance, has shown a link in promoting insulin resistance by inhibiting the action of insulin on various cellular functions from targeting keratinocytes, which is particularly relevant in psoriasis and PsA." (PMID 40137170, 2025). "Homocysteine impacts the insulin system by preventing the cleavage of the proinsulin receptor (pro-IR), resulting in insulin resistance." (PMID 40362226, 2025). "In IST-Cell, 14 miRNAs, such as those involved in endocrine resistance, insulin resistance, and insulin and glucagon signaling, were upregulate HBERs." (PMID 40549708, 2025). "Initially, insulin resistance is thought to result from iron accumulation in the liver and muscles, which increases insulin production." (PMID 39997354, 2025).
Insulin resistance (continued). "Insulin resistance, indicated by a reduced tissue response to insulin, is a critical mechanism in diabetes mellitus that begins as early as the prediabetes stage." (PMID 41023603, 2025). "Here, we analysed the effects of EVs from insulin-resistant individuals on insulin resistance in male mice; however, the effects in female mice remain to be determined." (PMID 39422717, 2025). "The brain's neuronal activity is altered by insulin insufficiency, compromised signalling, and insulin resistance." (PMID 40771585, 2025). "Insulin resistance (IR) denotes a pathological state wherein insulin target tissues – encompassing the liver, fat and muscle – exhibit markedly diminished responsiveness to insulin signals." (PMID 41348748, 2025). "Consistently, liver-specific expression of CA IKKβ impairs insulin signaling in hepatocytes and muscle cells, increases basal insulin and free fatty acid levels, and leads to systemic insulin resistance and glucose intolerance." (PMID 40562870, 2025). "The activation of PI3K/AKT can up-regulate the expression of GLUT4 and ameliorate insulin resistance, which is an insulin-mediated process." (PMID 40077469, 2025). "Type 2 Diabetes Mellitus (T2DM) is a chronic metabolic disease characterised by insulin resistance and defective insulin secretion, mainly manifested by elevated blood glucose." (PMID 40260282, 2025). "In line, it has been shown that male LKO mice develop insulin resistance and impaired insulin signaling in the liver." (PMID 39846638, 2025). "Other pathways include the insulin signaling pathway, genes regulating insulin resistance, and beta-cell proliferation, and hormonal regulation (leptin) interaction between the HPT axis and glucose metabolism." (PMID 40600010, 2025). "Diabetes mellitus is an epidemic chronic metabolic disorder characterized by persistent hyperglycemia resulting from inadequate insulin secretion and/or the development of insulin resistance." (PMID 40573309, 2025). "In summary, our findings suggest that a reduced ability to suppress FA mobilization from aSAT in response to insulin is an important contributor to whole‐body insulin resistance." (PMID 39487600, 2025). "The results demonstrated that the fasting blood glucose, serum insulin level, and insulin resistance index of mice with metabolic syndrome induced by a high‐fat and high‐fructose diet were all abnormally increased." (PMID 40708775, 2025). "Over the past decade, the concept of “central insulin resistance”, or impaired insulin action in the brain, has emerged as a central pathophysiological mechanism of neuroinflammation and neurodegeneration, particularly in the context of aging and T2DM." (PMID 40806709, 2025). "In particular, ER stress interferes with insulin signaling pathways, contributing to the development of metabolic diseases and insulin resistance." (PMID 41567335, 2025). "In the early stages of T2DM, increased insulin demand due to insulin resistance exacerbates ER stress in β-cells." (PMID 40166045, 2025). "Insulin resistance reduces tissue response to insulin stimulation, thereby inhibiting glucose uptake in the peripheral muscles and myocardium." (PMID 40297825, 2025). "Many studies have shown that the gut microbiota is closely related to glucose metabolism, insulin resistance, and insulin secretion." (PMID 40612440, 2025). "Elevated circulating placental hormones, including estrogen, progesterone, and growth hormone, decrease insulin sensitivity, prompting β-cells to secrete more insulin and contributing to insulin resistance." (PMID 40469674, 2025). "RV supplementation significantly reduced plasma glucose, insulin, homeostatic model assessment of insulin resistance, malondialdehyde, high-sensitivity C-reactive protein, tumor necrosis factor alpha, and interleukin-6." (PMID 41282017, 2025).